CKAP5 (cytoskeleton associated protein 5)
Description:
Binds to the plus end of microtubules and regulates microtubule dynamics and microtubule organization. Acts as a processive microtubule polymerase. Promotes cytoplasmic microtubule nucleation and elongation. Plays a major role in organizing spindle poles. In spindle formation protects kinetochore microtubules from depolymerization by KIF2C and has an essential role in centrosomal microtubule assembly independently of KIF2C activity. Contributes to centrosome integrity. Acts as a component of the TACC3/ch-TOG/clathrin complex proposed to contribute to stabilization of kinetochore fibers of the mitotic spindle by acting as inter-microtubule bridge. The TACC3/ch-TOG/clathrin complex is required for the maintenance of kinetochore fiber tension. Enhances the strength of NDC80 complex-mediated kinetochore-tip microtubule attachments.
Synonyms: Ch-TOG; KIAA0097; TOG; TOGp; CHTOG; MSPS
Tractability: Antibody: its Gene Ontology location is reachable by antibodies, with high confidence. PROTAC: ubiquitination databases record sites on it; its protein half-life has been measured.
Gene: Protein-coding gene on chromosome 11 (46,743,048 to 46,846,308, reverse strand). Ensembl gene ENSG00000175216.
Subcellular location: Cytoplasm, cytoskeleton, microtubule organizing center, centrosome; Cytoplasm, cytoskeleton, spindle pole; Cytoplasm, cytoskeleton, spindle; Chromosome, centromere, kinetochore
Subcellular location (Human Protein Atlas): Basal body; Centrosome; Mitotic spindle; Nucleoli; Nucleoli rim; Plasma membrane; Primary cilium
Pathways (Reactome):
Cell Cycle: AURKA Activation by TPX2; Amplification of signal from unattached kinetochores via a MAD2 inhibitory signal; EML4 and NUDC in mitotic spindle formation; Loss of Nlp from mitotic centrosomes; Loss of proteins required for interphase microtubule organization from the centrosome; Mitotic Prometaphase; Recruitment of NuMA to mitotic centrosomes; Recruitment of mitotic centrosome proteins and complexes; Regulation of PLK1 Activity at G2/M Transition; Resolution of Sister Chromatid Cohesion; Separation of Sister Chromatids
Organelle biogenesis and maintenance: Anchoring of the basal body to the plasma membrane
Signal Transduction: RHO GTPases Activate Formins
Gene Ontology:
Molecular function: cadherin binding; microtubule binding; protein binding; ribonucleoprotein complex binding; microtubule plus end polymerase; microtubule plus-end binding; tubulin binding
Biological process: centrosome cycle; establishment or maintenance of microtubule cytoskeleton polarity; positive regulation of microtubule nucleation; spindle organization; centrosome duplication; chromosome segregation; microtubule depolymerization; microtubule polymerization; mitotic cell cycle; mitotic spindle organization; RNA transport; protein-containing complex organization
Cellular component: centrosome; cytoplasm; kinetochore; membrane; microtubule plus-end; protein-containing complex; spindle pole; cytosol; kinetochore microtubule; microtubule cytoskeleton; mitotic spindle microtubule; spindle
Genetic constraint (gnomAD): Loss-of-function variants: 19 observed, 195.06 expected, observed/expected ratio (o/e) 0.0974, 90% interval 0.067 to 0.14. The upper end of that interval is the gene's LOEUF score, 0.14, which puts it in group 1 of 6, group 1 being the genes least tolerant of losing a copy. Missense variants: 1,661 observed, 2,303.7 expected, observed/expected ratio (o/e) 0.72, 90% interval 0.69 to 0.75. Synonymous variants: 703 observed, 811.8 expected, observed/expected ratio (o/e) 0.87, 90% interval 0.81 to 0.92.
Homologues: Orthologues: chimpanzee CKAP5 (99% identical), macaque CKAP5 (99% identical), pig CKAP5 (97% identical), rabbit CKAP5 (97% identical), dog CKAP5 (97% identical), guinea pig CKAP5 (96% identical), rat Ckap5 (95% identical), mouse Ckap5 (95% identical), tropical clawed frog ckap5 (81% identical), zebrafish ckap5 (75% identical), Drosophila melanogaster msps (40% identical), Caenorhabditis elegans F54A3.2 (10% identical), and 1 more.